SATB1 (SATB homeobox 1)
Description:
Crucial silencing factor contributing to the initiation of X inactivation mediated by Xist RNA that occurs during embryogenesis and in lymphoma (By similarity). Binds to DNA at special AT-rich sequences, the consensus SATB1-binding sequence (CSBS), at nuclear matrix- or scaffold-associated regions. Thought to recognize the sugar-phosphate structure of double-stranded DNA. Transcriptional repressor controlling nuclear and viral gene expression in a phosphorylated and acetylated status-dependent manner, by binding to matrix attachment regions (MARs) of DNA and inducing a local chromatin-loop remodeling. Acts as a docking site for several chromatin remodeling enzymes (e.g. PML at the MHC-I locus) and also by recruiting corepressors (HDACs) or coactivators (HATs) directly to promoters and enhancers. Modulates genes that are essential in the maturation of the immune T-cell CD8SP from thymocytes. Required for the switching of fetal globin species, and beta- and gamma-globin genes regulation during erythroid differentiation. Plays a role in chromatin organization and nuclear architecture during apoptosis. Interacts with the unique region (UR) of cytomegalovirus (CMV). Alu-like motifs and SATB1-binding sites provide a unique chromatin context which seems preferentially targeted by the HIV-1 integration machinery. Moreover, HIV-1 Tat may overcome SATB1-mediated repression of IL2 and IL2RA (interleukin) in T-cells by binding to the same domain as HDAC1. Delineates specific epigenetic modifications at target gene loci, directly up-regulating metastasis-associated genes while down-regulating tumor-suppressor genes. Reprograms chromatin organization and the transcription profiles of breast tumors to promote growth and metastasis. Promotes neuronal differentiation of neural stem/progenitor cells in the adult subventricular zone, possibly by positively regulating the expression of NEUROD1 (By similarity).
Synonyms: DEFDA; DHDBV; KTZSL
Tractability: PROTAC: UniProt records ubiquitination sites on it; ubiquitination databases record sites on it; its protein half-life has been measured.
Gene: Protein-coding gene on chromosome 3 (18,345,377 to 18,445,621, reverse strand). Ensembl gene ENSG00000182568.
Subcellular location: Nucleus matrix; Nucleus, PML body
Subcellular location (Human Protein Atlas): Nucleoplasm; Nuclear bodies
Pathways (Reactome):
Developmental Biology: Differentiation of naive CD4+ T cells to T helper 2 cells (Th2 cells)
Metabolism of proteins: SUMOylation of chromatin organization proteins
Programmed Cell Death: Apoptotic cleavage of cellular proteins
Gene Ontology:
Molecular function: DNA-binding transcription repressor activity, RNA polymerase II-specific; protein binding; RNA polymerase II transcription regulatory region sequence-specific DNA binding; sequence-specific DNA binding; DNA-binding transcription factor activity, RNA polymerase II-specific; double-stranded DNA binding; RNA polymerase II cis-regulatory region sequence-specific DNA binding; chromatin binding; DNA binding; DNA-binding transcription factor activity; DNA-binding transcription factor binding
Biological process: negative regulation of transcription by RNA polymerase II; chromatin organization; chromatin remodeling; regulation of transcription by RNA polymerase II
Cellular component: nuclear body; nuclear matrix; nucleoplasm; nucleus; PML body; chromatin; heterochromatin; nuclear lumen
Genetic constraint (gnomAD): Loss-of-function variants: 10 observed, 81.29 expected, observed/expected ratio (o/e) 0.12, 90% interval 0.075 to 0.21. The upper end of that interval is the gene's LOEUF score, 0.21, which puts it in group 1 of 6, group 1 being the genes least tolerant of losing a copy. Missense variants: 522 observed, 914.83 expected, observed/expected ratio (o/e) 0.57, 90% interval 0.53 to 0.61. Synonymous variants: 339 observed, 358.55 expected, observed/expected ratio (o/e) 0.95, 90% interval 0.86 to 1.03.
Gene-disease validity (ClinGen):
ClinGen rates the evidence that SATB1 causes each of these diseases.
complex neurodevelopmental disorder (autosomal dominant): Definitive. A disorder that involves more than one phenotype associated with the central nervous system, including but not limited to intellectual disability, autism, and seizures (epilepsy).
Homologues: Orthologues: chimpanzee SATB1 (100% identical), macaque SATB1 (99% identical), rabbit SATB1 (99% identical), mouse Satb1 (98% identical), rat Satb1 (98% identical), guinea pig SATB1 (98% identical), dog SATB1 (97% identical), pig SATB1 (92% identical), tropical clawed frog satb1 (87% identical), zebrafish satb1b (73% identical), Drosophila melanogaster dve (22% identical), Caenorhabditis elegans dve-1 (14% identical). Paralogues in human: SATB2 (57% identical).
Diseases named in the same sentence as SATB1 in open-access papers:
SATB1 is named in the same sentence as 139 diseases in open-access papers, as found by Europe PMC text mining. Sharing a sentence is not in itself a finding about the gene and the disease. The quoted sentences say what the papers report.
breast carcinoma (73 papers, 2009 to 2025). "Aberrant SATB1 expression is associated with various cancers, including breast cancer, lung cancer, and CRC." (PMID 40071088, 2025). "SATB1 has been implicated in the development, invasion, and metastasis of several cancer types, including breast cancer, CRC, gastric cancer, pancreatic cancer, OC, endometrial cancer, and cervical cancer." (PMID 40071088, 2025). "SATB1 is also regulated by miR-21, a well-known oncogenic miRNA implicated in various cancers, including glioblastoma, lung cancer, gastric cancer, breast cancer, liver cancer, cervical cancer, and ovarian cancer." (PMID 40071088, 2025). "further validated SATB1’s role in breast cancer progression, associating its high expression with an advanced tumor stage, lymph node metastasis, and decreased survival rates." (PMID 40071088, 2025). "initially reported that high SATB1 expression was linked to poorer OS in patients with breast cancer." (PMID 40071088, 2025). "SATB1 seems to be upregulated in malignant tumors of the breast, colon, and bladder cancer causing aggressive tumor growth and limited prognosis." (PMID 34961766, 2021). "Han and co-workers observed that a high SATB1 level was strongly associated with a shorter overall survival (OS) time of breast cancer patients." (PMID 31450715, 2019). "A number of studies have found a significant association between SATB1′s expression and the metastatic potential and aggressiveness of breast cancer cells." (PMID 31450715, 2019). "In breast cancer, SATB1 was found to directly upregulate metastasis-associated genes while it decreased expression of tumor-suppressor genes and promoted tumor growth and metastasis." (PMID 25874491, 2015). "According to correlation analysis, the expression of SATB1 was associated with higher histological grade in patients with breast cancer (r = 0.239, p = 0.002)." (PMID 25956130, 2015). "SATB1 expression was shown to markedly alter the expression of over 1000 breast cancer genes including metastasis-associated genes and tumor suppressor genes." (PMID 24971456, 2014). "miR-191 mediated downregulation of SATB1 has been linked to gain/loss of epithelial/mesenchymal markers in aggressive breast cancer and enhanced cell proliferation and migration in hormone dependent breast cancer." (PMID 24795757, 2014). "Knockdown of SATB1 in aggressive breast cancer cell lines caused complete reversal of tumor growth and metastatic abilities in vivo and introduction of SATB1 decoy DNA drastically reduced invasive and metastatic capacity of SATB1-positive cell lines." (PMID 25326863, 2014). "SATB1 expression markedly altered the expression of over 1000 breast cancer genes including metastasis-associated genes and tumor suppressor genes to promote growth and metastasis of breast tumor." (PMID 24971456, 2014). "The SATB1 -3600T/-3363A/-2984C haplotype is associated with lower promoter activity and appears to impact upon survival in breast cancer patients." (PMID 24932280, 2014). "Several polymorphisms in the SATB1 promoter region were identified, and the accordant haplotypes were found to alter the promoter activity and overall survival rates of breast cancer patients." (PMID 24932280, 2014). "SATB1 promotes tumor growth and metastasis in breast cancer and is associated with poor prognosis in several cancer types." (PMID 24971456, 2014). "Recent studies suggest that SATB1 modulates cell proliferation and lineage development and is implicated in breast cancer." (PMID 23642278, 2013). "SATB1 mRNA expression is significantly associated with poor prognostic parameters in breast cancer, including increasing tumour grade, TNM stage and NPI." (PMID 19642980, 2009). "Further studies have reinforced the association between SATB1 and breast cancer aggressiveness." (PMID 40071088, 2025).
breast carcinoma (continued). "In addition, aggressive breast cancer cells are found to express high levels of SATB1 gene, which was found to be closely linked (p < 0.0001) with prognostic outcomes of cancer patients." (PMID 31783698, 2019). "In addition to nuclear receptor mediated long-range interactions, increased expression of the architectural protein SATB1, which participates in chromatin loop formation, alters the expression of over 1000 genes and is associated with aggressive breast cancer." (PMID 24019942, 2013). "SATB1, a genome organizer that recruits chromatin-remodelling enzymes to regulate chromatin structure and gene expression, has been recently implicated to promote growth and metastasis of breast cancer and indicate poor prognosis." (PMID 22424533, 2012). "The present study screened the promoter region of the SATB1 gene for polymorphisms, evaluated the corresponding haplotypes regarding alterations in promoter activity in vitro and analyzed the impact of these haplotypes on the clinical course of breast cancer patients." (PMID 24932280, 2014). "In this study, the promoter region of the SATB1 gene was screened for polymorphisms, the corresponding haplotypes regarding alterations in promoter activity in vitro were evaluated, and the impact of these haplotypes on the clinical course of breast cancer patients was analyzed." (PMID 24932280, 2014). "Furthermore, recent reports have expanded the association of SATB1 with multiple types of tumors in addition to breast cancer, such as laryngeal squamous cell carcinoma, endometriod endometrial cancer, hepatocellular carcinoma, rectal cancer, cutaneous malignant melanoma, and gastric cancer." (PMID 23251624, 2012). "SATB1 has been identified as a key regulator in breast cancer progression and metastasis through its role in reprogramming gene expression networks." (PMID 40071088, 2025). "A study in breast cancer stem cells reported a similar correlation, wherein SATB1 led to the upregulation of Snail1 and Twist1 through the activation of Notch signaling." (PMID 40689929, 2025). "In summary, while inconsistencies exist in the literature, most evidence points to SATB1 as a key player in breast cancer progression and metastasis." (PMID 40071088, 2025). "H19 sponges miRNA-130a-3p, resulting in SATB1 upregulation, thus promoting breast cancer progression." (PMID 40071088, 2025). "in 2008 laid the foundation for understanding SATB1’s involvement in breast cancer, showing that SATB1 mRNA and protein are predominantly expressed in metastatic breast cancer cell lines compared with non-malignant breast tissues." (PMID 40071088, 2025). "For example, miR-191-5p regulates cortical development by targeting brain-derived neurotrophic (factor BDNF), and promotes the proliferation and migration of human breast cancer cells by targeting special AT-rich sequence-binding protein-1 (SATB1)." (PMID 39469460, 2024). "To further address this, we utilized the TCGA breast cancer dataset (BRCA) as a cancer tissue expressing SATB1." (PMID 37635874, 2023). "ATAC-seq experiments for human patients with aggressive breast cancer revealed differences in chromatin accessibility at the extra exon of the SATB1 gene." (PMID 37635874, 2023). "Whereas in breast cancer, the expression of miR-191 increased, and increased expression of miR-191 promotes the proliferation and migration of breast cancer cells by targeting SATB1." (PMID 37460940, 2023). "Previous studies have found that SATB1 has an important function to regulate invasion and metastasis in breast cancer." (PMID 37540226, 2023). "More specifically, the presence of SATB1 was known to interact with and upregulate genes responsible for poor prognosis in breast cancer." (PMID 35812421, 2022). "The chromatin organiser and transcriptional regulator “Special AT-rich binding protein 1” (SATB1) has been shown to be expressed during tumorigenesis and to affect the gene expression profile of breast cancer cells." (PMID 33572976, 2021).
breast carcinoma (continued). "SATB1 has also been identified to promote drug-induced EMT in breast cancer cell lines, driven by the positive feedback regulation of miR-448 and NF-κB signaling." (PMID 33390772, 2021). "Baicalein inhibited the migration of MDA-MB-231 breast cancer cells by suppressing SATB1, a nuclear matrix binding protein, and the Wnt/β-catenin pathway in a dose-dependent manner." (PMID 35056061, 2021). "On the other hand, SATB1 is overexpressed during tumorigenesis and alters the gene expression profile of breast cancer cells, supporting an aggressive phenotype promoting tumor growth and metastasis (for review)." (PMID 33572976, 2021). "SATB1 has been shown in breast carcinoma to affect the expression of HER receptors and was found upregulated in gastric cancer." (PMID 33374770, 2020). "SATB1 and its mRNA were only detected in metastatic breast cancer cell lines, and their levels were correlated with the aggressiveness of the cells." (PMID 31450715, 2019). "In this study, we focused on the special AT rich binding protein 1 (SATB1) gene, which was reported to have dual functions, one of which was to induce aggressive growth in breast cancer cells." (PMID 31783698, 2019). "Hanker and colleagues analysed SATB1′s expression using Affymetrix microarrays in a cohort of more than 2000 breast cancer samples." (PMID 31450715, 2019). "SATB1′s level increased gradually during the progression from non-malignant breast tissue, through cystic hyperplasia and precancerous lesions, to breast cancer at the end." (PMID 31450715, 2019). "They demonstrated that siRNA-mediated SATB1 silencing in highly aggressive MDA-MB-231 breast cancer cells resulted in a significant reduction of their invasive capacity and prevented the formation of colonies." (PMID 31450715, 2019). "They analysed 10 studies involving a total of 5185 patients, and the showed that SATB1′s expression positively correlated with breast cancer progression." (PMID 31450715, 2019). "It has been demonstrated that SATB1-dependent gene sets in breast cancer cells and mouse primary keratinocytes have only minimal overlap." (PMID 31450715, 2019). "Many attempts have been made in order to define the prognostic value of SATB1′s expression in mammary tumours." (PMID 31450715, 2019). "In 2016, Pan and colleagues performed a meta-analysis to summarize the clinical and prognostic relevance of SATB1′s expression in mammary tumours." (PMID 31450715, 2019). "Further study will be conducted to investigate the molecular functions of and the role of SATB1 in 4T1 mammary cancer cells and DC." (PMID 31783698, 2019). "Lastly, we show the utility of iTextMine with two use cases: PTEN and breast cancer and regulation and disease involvement of SATB1, a protein involved in regulating chromatin remodeling." (PMID 30576489, 2018). "We demonstrate the utilities of iTextMine with two use cases involving the gene PTEN and breast cancer and the gene SATB1." (PMID 30576489, 2018). "It is already known that SATB1 is an oncogene which promotes breast tumor growth and metastasis; its expression was reported in several breast cancer cell lines and tumor biopsies." (PMID 28147311, 2017). "We demonstrated that SATB1 functions differently in esophagus cancer versus breast cancer by comparing their gene expression profiles." (PMID 28147311, 2017). "The majority of GO enriched pathways were different between TE-1 and MDA-MB-231 cells, further suggesting SATB1 has different regulatory function in esophageal cancer cells and breast cancer cells." (PMID 28147311, 2017). "Silencing of SATB1 expression in breast cancer cell lines restored normal acinar polarity and limited the ability of cells to grow and metastasize in vivo." (PMID 25874491, 2015). "Although SATB1 overexpression has been previously demonstrated to increase breast cancer invasion and metastasis, its effect on the stem cell population remains to be fully elucidated." (PMID 25586771, 2015).